TMPRSS11GP (transmembrane serine protease 11G, pseudogene)
Gene: Transcribed unitary pseudogene on chromosome 4 (67,991,684 to 68,015,768, reverse strand). Ensembl gene ENSG00000229009.
Diseases named in the same sentence as TMPRSS11GP in open-access papers:
TMPRSS11GP is named in the same sentence as 1 disease in open-access papers, as found by Europe PMC text mining. Sharing a sentence is not in itself a finding about the gene and the disease. The quoted sentences say what the papers report.
tumor (1 paper, 2020). "The results showed that the expressions of AC112721.1 and ADAMTS9-AS1 were significantly associated with lymph node metastasis, tumor grade, and pathologic stage of BC (P<0.05), while the expression of TMPRSS11GP was significantly associated with age and tumor grade (P<0.05)." (PMID 33169791, 2020).